OAS1 (2'-5'-oligoadenylate synthetase 1)
Description:
Interferon-induced, dsRNA-activated antiviral enzyme which plays a critical role in cellular innate antiviral response. In addition, it may also play a role in other cellular processes such as apoptosis, cell growth, differentiation and gene regulation. Catalyzes the formation of 2'-5'-oligoadenylates (2-5A) from polymerization of ATP which then bind to the inactive monomeric form of ribonuclease L (RNase L) leading to its dimerization and subsequent activation. Activation of RNase L leads to degradation of cellular as well as viral RNA, resulting in the inhibition of protein synthesis, thus terminating viral replication. Involved in intercellular immune signaling that limits local spread of RNA virus infection and protects against tumorigenesis. Can generate high levels of 2',5'-oligoadenylates in transformed cells, targeting them to innate and adaptive immunesurveillance mechanisms. Can mediate the antiviral effect via the classical RNase L-dependent pathway or an alternative antiviral pathway independent of RNase L. The secreted form displays antiviral effect against vesicular stomatitis virus (VSV), herpes simplex virus type 2 (HSV-2), and encephalomyocarditis virus (EMCV) and stimulates the alternative antiviral pathway independent of RNase L. [Isoform p46]: When prenylated at C-terminal, acts as a double-stranded RNA (dsRNA) sensor specifically targeted to membranous replicative organelles in SARS coronavirus-2/SARS-CoV-2 infected cells where it binds to dsRNA structures in the SARS-CoV-2 5'-UTR and initiates a potent block to SARS-CoV-2 replication. Recognizes short stretches of dsRNA and activates RNase L. The binding is remarkably specific, with two conserved stem loops in the SARS-CoV-2 5'-untranslated region (UTR) constituting the principal viral target. The same mechanism is necessary to initiate a block to cardiovirus EMCV. [Isoform p42]: Not prenylated at C-terminal, is diffusely localized and unable to initiate a detectable block to SARS-CoV-2 replication.
Synonyms: OIAS; OIASI; IFI-4; E18/E16; IMD100
Tractability: Small molecule: a structure with a bound ligand is known. Antibody: UniProt places it where antibodies can reach, with medium confidence; its Gene Ontology location is reachable by antibodies, with medium confidence. PROTAC: ubiquitination databases record sites on it; its protein half-life has been measured.
Gene: Protein-coding gene on chromosome 12 (112,905,856 to 112,933,219, forward strand). Ensembl gene ENSG00000089127.
Subcellular location: Cytoplasm; Mitochondrion; Nucleus; Microsome; Endoplasmic reticulum; Secreted; Note=(Microbial infection) In SARS coronavirus-2/SARS-CoV-2 infected cells, prenylated form localizes to membranous perinuclear structures reminiscent of the endoplasmic reticulum rich in viral dsRNA which are SARS-CoV-2 replicative organelles (Isoform p46); Note=(Microbial infection) In SARS coronavirus-2/SARS-CoV-2 infected cells, since its not prenylated, is diffusely localized and unable to initiate a detectable block to SARS- CoV-2 replication (Isoform p42)
Subcellular location (Human Protein Atlas): Cytosol; Nucleoplasm
Pathways (Reactome):
Immune System: Interferon alpha/beta signaling; Interferon gamma signaling; OAS antiviral response
Gene Ontology:
Molecular function: 2'-5'-oligoadenylate synthetase activity; double-stranded RNA binding; protein binding; ATP binding; nucleotidyltransferase activity
Biological process: antiviral innate immune response; cellular response to exogenous dsRNA; cellular response to interferon-beta; cellular response to virus; defense response to bacterium; defense response to virus; glucose homeostasis; glucose metabolic process; interleukin-27-mediated signaling pathway; negative regulation of chemokine (C-X-C motif) ligand 2 production; negative regulation of IP-10 production; negative regulation of type I interferon-mediated signaling pathway; negative regulation of viral genome replication; positive regulation of interferon-beta production; positive regulation of monocyte chemotactic protein-1 production; positive regulation of tumor necrosis factor production; response to virus; surfactant homeostasis; toll-like receptor 3 signaling pathway; toll-like receptor 4 signaling pathway; type I interferon-mediated signaling pathway; defense response
Cellular component: cytoplasm; cytosol; nucleoplasm; nucleus; extracellular region; membrane; endoplasmic reticulum; mitochondrion
Genetic constraint (gnomAD): Loss-of-function variants: 22 observed, 38.43 expected, observed/expected ratio (o/e) 0.57, 90% interval 0.41 to 0.82. The upper end of that interval is the gene's LOEUF score, 0.82, which puts it in group 3 of 6, group 1 being the genes least tolerant of losing a copy. Missense variants: 476 observed, 509.61 expected, observed/expected ratio (o/e) 0.93, 90% interval 0.87 to 1.01. Synonymous variants: 165 observed, 201.37 expected, observed/expected ratio (o/e) 0.82, 90% interval 0.72 to 0.93.
Homologues: Orthologues: macaque OAS1 (90% identical), chimpanzee OAS1 (82% identical), dog OAS1 (68% identical), mouse Oas1g (63% identical), mouse Oas1a (62% identical), rabbit OAS1 (62% identical), rat Oas1a (62% identical), guinea pig OAS1 (61% identical), rat Oas1k (60% identical), rat Oas1b (56% identical), pig OAS1 (52% identical), mouse Oas1b (52% identical), and 9 more. Paralogues in human: OAS3 (52% identical), OAS2 (47% identical), OASL (36% identical).
Diseases named in the same sentence as OAS1 in open-access papers:
OAS1 is named in the same sentence as 159 diseases in open-access papers, as found by Europe PMC text mining. Sharing a sentence is not in itself a finding about the gene and the disease. The quoted sentences say what the papers report.
COVID-19 (149 papers, 2020 to 2026). A disease caused by infection with severe acute respiratory syndrome coronavirus 2. "Overall, our findings suggest that OAS1 acts as a susceptibility factor for COVID-19 and the rs1131454A>G and rs10735079A>G SNVs are associated with sore throat in the Mexican population." (PMID 41977153, 2026). "Logistic regression analysis adjusted for age and sex revealed an association between the OAS1 rs10774671A risk allele and susceptibility to COVID-19 (G vs. A: OR = 1.9, p = 0.007)." (PMID 41977153, 2026). "These 76 include an OAS1 sQTL variant that was identified 20 years ago but has undergone increased interest due to its association with severe COVID-19." (PMID 41542048, 2026). "The relevance of such tQTLs in disease is demonstrated by our observation of rs57484342 at the OAS1 COVID-19 severity risk locus associated with divergent OAS1 splicing post-IFN-γ exposure, a condition akin to early-onset viral infection." (PMID 41022800, 2025). "The association between TLR7 and OAS1 expression with COVID-19 severity was especially relevant among the significant results obtained." (PMID 41445728, 2025). "Studies of OAS1 in relation to COVID-19 response identified the association of rs10774671, an SNP governing alternative exon usage." (PMID 39859237, 2025). "OAS1 is a viral response gene, interferon-induced, dsRNA activated enzyme, which binds RNase L to degrade dsRNA, and has been associated with COVID-19 response." (PMID 39859237, 2025). "This study highlights the role of TLR7 and OAS1 expression in COVID-19, revealing associations with viral load and severity." (PMID 41445728, 2025). "Further to this, the authors noted that OAS1 variants were also associated with COVID-19 response, and the SNPs were in strong linkage disequilibrium with the AD-associated SNP presented in their study." (PMID 39859237, 2025). "OAS1 has long been known to play a role in the response to viral infection and diabetes risk, and has recently been implicated in COVID-19 severity." (PMID 41274869, 2025). "In summary, current evidence underscores the significance of genetic variation within the OAS1 gene in influencing susceptibility to and severity of COVID-19." (PMID 40543387, 2025). "The study identified a common haplotype associated with reduced OAS1 expression, which correlated with greater COVID-19 severity." (PMID 40543387, 2025). "Recent studies have illuminated the role of genetic variants within the OAS1 gene in modulating COVID-19 severity, particularly among individuals of European and African descent." (PMID 40543387, 2025). "Low TLR7 levels were associated with severe COVID-19, and together with OAS1 expression were modulated over time according to severity." (PMID 41445728, 2025). "A recent study shows how two typical human OAS1 gene polymorphisms (rs1131454 and rs10774671) are abundant in European and African COVID-19 patients who need to be hospitalized." (PMID 40002189, 2025). "For the OAS1 rs10774671 gene variant, the log-additive model showed a significant association with the severe phenotype of COVID-19 (P=0.0084, OR=3.85, 95% CI 1.33-11.12)." (PMID 38694517, 2024). "Polymorphisms in genes such as OAS1 have garnered particular attention due to their potential influence on COVID-19 outcomes." (PMID 39171921, 2024). "Their study suggested that this polymorphism’s functional impact on OAS1 protein abundance contributes to its association with COVID-19 hospitalization outcomes." (PMID 39296547, 2024). "A genetic study conducted on patients of European ancestry identified a risk locus for severe COVID-19 in the 2’-5’-oligoadenylate synthetase 1/2/3 (OAS1/2/3) gene cluster." (PMID 38658463, 2024). "From a genetic perspective, some genes such as APOE4 and oligoadenylate synthetase 1 (OAS1) play important roles in susceptibility to both COVID-19 and AD." (PMID 39174535, 2024).
COVID-19 (continued). "On the other hand, the OAS1 gene is located at 12q24.13, a chromosomal region previously associated with the severe form of COVID-19 in genome-wide association studies." (PMID 38694517, 2024). "The G allele OAS1 rs10774671 was used in logistic regression as a predictor of COVID-19 severity (p = 0.052)." (PMID 39296547, 2024). "Further analysis revealed that susceptibility to severe COVID-19 is associated with a SNP (single-nucleotide polymorphism) in the OAS1 gene, which results in the OAS1 isoform being expressed as p42 or p46." (PMID 38343534, 2024). "In contrast, a previous study focused on pediatric patients reported that those with the G/C genotype of OAS1 exhibited a 0.18-fold reduction in the risk of COVID-19, suggesting a protective effect." (PMID 38673053, 2024). "Recent studies point to the association of the OAS1 gene, as well as rs10774671, with the severity of COVID-19." (PMID 38543725, 2024). "Banday found that rs10774671-A and rs1131454-A formed a common haplotype, which decreased OAS1 expression and contributed to COVID-19 severity through allele-specific regulation of splicing and nonsense-mediated decay in European and African populations." (PMID 38429664, 2024). "Subsequently, it was reported that elevated levels of OAS1 in the plasma were associated with reduced COVID-19 susceptibility and severity." (PMID 38658463, 2024). "The OAS1 rs10774671-G allele has been shown to increase levels of the p46 isoform, and thus, the circulating levels of the OAS1 protein are strongly associated with a reduced risk of severe COVID-19." (PMID 38658463, 2024). "The rs10774671-G allele of OAS1 confers protection against severe COVID-19 in the Moroccan population." (PMID 38658463, 2024). "Still, the severity of viral disease seems to be increasingly linked to variability in the repertoires of expressed ISGs as evidenced by isoforms of OAS1 as well as OAS1 loss-of function alleles associated with distinct outcomes in COVID-19 patients." (PMID 39475961, 2024). "Noteworthy, two brothers with mild COVID-19 (P20 and P21) carried a heterozygous variant (p.P301L) in the OAS1 gene." (PMID 36880831, 2023). "On the contrary, OAS1 risk alleles for AD and severe COVID-19 are all linked with decreased OAS1 expression, which exaggerates the production of TNF-α with IFN-γ stimulation." (PMID 36717892, 2023). "A common haplotype comprised of derived human risk alleles of two OAS1 expression variants is associated with the risk of hospitalized COVID-19 in patients of European and African ancestries, compared to non-hospitalized patients." (PMID 37364688, 2023). "Up-regulation of the p46 splice variant of OAS1 has been specifically associated with protection against severe COVID-19." (PMID 36241425, 2023). "We first replicated the association of COVID-19 outcomes with OAS1 splicing, using an updated version of COVID-19 HGI release 7, which provides a 10-fold increase in case sample size." (PMID 37794074, 2023). "They propose that the functional impact of rs10774671 contributes to the association with COVID-19 severity by modulating the abundance of the OAS1 protein." (PMID 37632067, 2023). "Genetic regulation of OAS1 nonsense-mediated decay underlies the association with COVID-19 hospitalization." (PMID 37364688, 2023). "We perform fine-mapping of the OAS1 locus, associated with COVID-19, to reveal the imbalanced expression of OAS1 and OAS3 genes during the antiviral innate immune response." (PMID 37308670, 2023). "Strikingly, oligoadenylate synthetase 1 (OAS1), a newly reported risk gene for AD, was recently identified as a putative risk gene associated with severe COVID-19 in intensive care patients in human genome-wide association studies." (PMID 36717892, 2023). "A recent study has demonstrated that a variant of the oligoadenylate synthetase 1 (OAS1) gene expressed in microglia is involved in the higher risk for AD and severe neurological complications of COVID-19." (PMID 37163427, 2023).
COVID-19 (continued). "Finally, these studies support the potential utility of the CASQ sequence for probing the importance of CAAX proteolysis in other protein contexts, such as Rho, lamins, and the double-stranded RNA sensor Oas1 that is implicated in coronavirus disease 2019 risk (30, 53, –, 56)." (PMID 36602340, 2023). "Their study identified single nucleotide polymorphisms of the OAS1 gene to be associated with both increased risk of AD and predisposition to severe COVID-19." (PMID 36717892, 2023). "Recently, Banday and colleagues showed that another SNP in exon 3 of the human OAS1 gene associated with increased hospitalisation of COVID-19 patients produces isoforms with a shortened exon 3 start." (PMID 38015855, 2023). "The influences of allele A OAS1 rs10774671 on COVID-19 susceptibility and its severe course were confirmed by two logistic models." (PMID 37896870, 2023). "Since MX1, MX2, ISG15, and OAS1 showed a similar expression pattern in COVID-19-positive patients, we next evaluated the association of their combined expressions with viral load." (PMID 36298734, 2022). "A common polymorphism in OAS1 (rs10774671), where the protective allele resulted in a more active OAS1 enzyme, probably led to less severe COVID-19." (PMID 36204639, 2022). "Our MR results suggest that both the OAS1 gene expression level and its splice variation are causal for COVID-19 severity." (PMID 36424512, 2022). "Additional MR analysis using rs10774671 as the instrumental variable demonstrated that splice variation of OAS1 is also causal for COVID-19 severity (p = 4e−6)." (PMID 36424512, 2022). "Among them, an overlap has been found between genetic risk factors for AD and severe COVID-19, such as single-nucleotide polymorphisms (SNPs) in oligoadenylate synthetase 1 (OAS1) and bridging integrator 1 (BIN1) genes." (PMID 35055344, 2022). "In our study, the risk of hospitalization for COVID-19 in patients of European and African ancestries was associated with a haplotype encompassing part of the OAS1 region (~14 kb)." (PMID 35835913, 2022). "We propose that rs10774671 and rs1131454 functionally contribute to the association with COVID-19 severity by regulating the abundance of OAS1 protein." (PMID 35835913, 2022). "The other association is with a cluster of introgressed genetic variants on chromosome 12 overlapping the OAS1-2-3 locus that shows a protective effect against severe COVID-19 response (Zeberg and Pääbo 2020b)." (PMID 34662402, 2022). "We tested 63 SNPs in the vicinity of OAS1-2-3 directly falling within the severe COVID-19 protective locus in strong LD with the lead GWAS variant (r2 = 0.98; 1000 Genomes GBR) and six additional variants in moderate LD with the lead variant (r2 ≥ 0.5)." (PMID 34662402, 2022). "We demonstrated that a common haplotype comprised of derived human-specific risk alleles of two OAS1 variants is associated with the risk of hospitalized COVID-19 in patients of European and African ancestries, compared to nonhospitalized patients." (PMID 35835913, 2022). "For OAS1, both predicted and measured protein levels are inversely associated with COVID-19 susceptibility and severity, which is consistent with the current study’s findings." (PMID 36284135, 2022). "One of the variants associated with COVID-19 severity in both ancestries, an OAS1 intronic/intergenic variant rs4767027, has been reported as a protein quantitative trait locus (pQTL) for OAS1 blood levels in the European population." (PMID 35835913, 2022). "In this preliminary study of 58 patients, we genotyped three variants that capture OAS1 haplotypes associated with COVID-19 hospitalization in our case–case analyses: rs1131454, rs10774671, and rs2660." (PMID 35835913, 2022). "Clinical studies have shown that elevated levels of plasma OAS1 are associated with reduced COVID-19 hospitalization and mortality; these effects are amplified by an OAS1 isoform of Neanderthal origins." (PMID 35421191, 2022).